EBI3 (Epstein-Barr virus induced 3)
Diseases named in the same sentence as EBI3 in open-access papers (continued):
Sharing a sentence is not in itself a finding about the gene and the disease.
Epstein-Barr virus infection (1 paper, 2022). An infection that is caused by Epstein-Barr virus. "EBI3 has been identified as a hematopoietic receptor-like protein induced in B cells by Epstein-Barr virus infection." (PMID 34782759, 2022).
follicular lymphoma (1 paper, 2011). Follicular lymphoma is a form of non-Hodgkin lymphoma characterized by a proliferation of B cells whose nodular structure of follicular architecture is preserved. "To further investigate the in vivo effect of c-myc translocation on EBI3 expression, we analyzed the expression of EBI3 by immunohistochemistry in a case of follicular lymphoma that had acquired c-myc translocation during transformation." (PMID 21931777, 2011). "In a previous report, we had observed that in follicular lymphomas, EBI3 was expressed by tumoral cells, mainly large cells, at a variable level that could reach up to 30% of tumoral cells." (PMID 21931777, 2011). "Previously, we have shown that EBI3 expression by tumoral cells is lower in follicular lymphomas (from 1 to 30% positive tumoral cells at the most) than in DLBCL, and remains lower (less than 30% positive tumoral cells) in established transformed follicular lymphomas (our unpublished data)." (PMID 21931777, 2011). "Whereas a substantial fraction of tumoral cells stained positive for EBI3 in the follicular lymphoma, tumoral cells were all negative for EBI3 in the c-myc-positive transformed counterpart." (PMID 21931777, 2011). "The negativity for EBI3 expression among DLBCL cases may also be due to the fact that some of them may arise from transformed follicular lymphomas, an event that is not always diagnosed." (PMID 21931777, 2011).
gastritis (1 paper, 2013). Inflammation of the stomach. "Considering the effect of H. pylori infection on the immunoreactivity of IL-12 and Ebi3 in gastritis, our qualitative assessment of the selected cases revealed similar staining patterns regardless of H. pylori infection." (PMID 24069393, 2013). "To examine protein expression of IL-12, p19, and Ebi3 in gastric biopsies of gastritis cases we used IHC." (PMID 24069393, 2013). "In a proof-of-principle experiment, we demonstrated epithelial-derived expression of IL-12, p19, and Ebi3 in gastric mucosa of gastritis patients using immunohistochemistry (IHC)." (PMID 24069393, 2013).
Headache (1 paper, 2021). Cephalgia, or pain sensed in various parts of the head, not confined to the area of distribution of any nerve. "And there was associations between the polymorphisms of the EBI3 rs4740 and the occurrence of headache or tinnitus in VKH patients." (PMID 34950136, 2021). "Our results shown that there were associations between the polymorphisms of EBI3 rs4740 and the occurrence of headache and tinnitus of VKH patients, respectively." (PMID 34950136, 2021). "In addition, there were associations between the polymorphisms of EBI3 rs4740 and the occurrence of headache and tinnitus of VKH patients, respectively." (PMID 34950136, 2021). "There was a statistical difference in allele frequency of the EBI3 rs4740 between VKH patients with headache and without it (χ2 = 7.291, p = 0.012)." (PMID 34950136, 2021).
Hepatitis (1 paper, 2013). Inflammation of the liver. "For instance, WSX-1−/− mice exhibited enhanced liver inflammation, whereas EBI3−/− mice showed reduced liver inflammation in the same Con A-induced hepatitis animal model." (PMID 24068935, 2013).
hyperuricemia (1 paper, 2017). An abnormally high level of uric acid. "However, in healthy controls only the EBI3 rs428253 correlates with increased risk of hyperuricemia." (PMID 28321150, 2017).
influenza infection (1 paper, 2019). "Our data suggests Ebi3−/− mice are more susceptible to influenza infection as revealed by weight loss, mortality curve and increased collagen deposition in the lung tissue as detected by Masson’s trichrome staining." (PMID 30899058, 2019). "We found that NK cells from Ebi3−/− as well as Il27ra−/− mice have reduced MafF expression with the highest fold change during influenza infection." (PMID 30899058, 2019). "We confirmed gene array data using RT-qPCR analyses of c-Maf, MafF, and MafK expression in sorted NK cells from influenza-infected WT and Ebi3−/− mice." (PMID 30899058, 2019). "Towards this, we purified NK cells from WT, and Ebi3−/− mice on DPI 4 following influenza infection, purified mRNA, and performed gene array analyses for a panel of 48 transcription factors using Biomark chips." (PMID 30899058, 2019). "Ebi3−/− mice displayed reduced IFN-γ production at the transcriptional level, suggesting IL-27 regulates NK cells responses at an early phase of influenza infection." (PMID 30899058, 2019). "Ebi3−/− and Il27ra−/− mice exhibited significantly reduced NK cell effector functions (IFN-γ and cytotoxicity) during influenza infection." (PMID 30899058, 2019).
melanoma in situ (1 paper, 2013). "Of 9 cases of melanoma in situ, 8 cases were largely negative for EBI3." (PMID 24130734, 2013).
metabolic syndrome (1 paper, 2017). A cluster of metabolic risk factors for CARDIOVASCULAR DISEASES and TYPE 2 DIABETES MELLITUS. "These polymorphisms were also associated with decreased risk of T2DM (EBI3 rs428253) and metabolic syndrome (IL-12A rs2243115) in premature CAD patients." (PMID 28321150, 2017).
Miscarriage (1 paper, 2025). A pregnancy that ends at a stage in which the fetus is incapable of surviving on its own, defined as the spontaneous loss of a fetus before the 22th week of pregnancy. "Although we did not observe a protective effect against miscarriage, administering a single rIL-35 and anti-Ebi3 neutralizing antibody dose induced numerous effects on regulatory B and T lymphocytes at the local and peripheral levels." (PMID 41346623, 2025).
nevus (1 paper, 2013). Nevus (or naevus, plural nevi or naevi, from nævus, Latin for "birthmark") is the medical term for sharply circumscribed[1] and chronic lesions of the skin or mucosa. "In particular, nevus cells localized in junctional or intradermal nevi were negative for EBI3." (PMID 24130734, 2013).
osteoarthritis (1 paper, 2022). A noninflammatory degenerative joint disease occurring chiefly in older persons, characterized by degeneration of the articular cartilage, hypertrophy of bone at the margins and changes in the synovial membrane. "To examine the expression of EBI3 and its relevance to ER stress in MSCs under inflammatory conditions in vivo, we firstly stained synovial tissue from RA and osteoarthritis (OA) patients with antibodies to detect CD271 (a promising marker for MSC), CD105 (a marker used for MSC isolation), and EBI3." (PMID 36548354, 2022).
peritonitis (1 paper, 2020). Inflammation of the peritoneum (tissue that lines the abdominal wall and covers most of the organs in the abdomen). "Improved infection control in adult mice lacking EBI3 or IL-27Rα occurs during both M. tuberculosis and P. aeruginosa infections or CLP-induced peritonitis." (PMID 31818960, 2020).
pulmonary hypertension (1 paper, 2025). Increased pressure within the pulmonary circulation due to lung or heart disorder. "The transplantation of Tregs effectively ameliorated pulmonary hypertension, with a reduced therapeutic efficacy observed in mice subjected to EBI3 knockout or treated with IL-35 antibodies." (PMID 39974277, 2025).
sarcoidosis (1 paper, 2020). Sarcoidosis is a multisystemic disorder of unknown cause characterized by the formation of immune granulomas in involved organs. "The results showed that the relative gene expression of EBI3 in CD19+ B cells of patients with active sarcoidosis was significantly higher as compared to patients with stable sarcoidosis (P=0.032) and the control group (P = 0.032)." (PMID 32508842, 2020).
scleroderma (1 paper, 2023). Scleroderma is a rare autoimmune connective tissue disorder characterized by abnormal hardening of the skin and, sometimes, other organs. "Additionally, EBI3 downregulation contributes to type I collagen overexpression in scleroderma skin." (PMID 37480105, 2023).
skin cutaneous melanoma (1 paper, 2024). "Notably, skin cutaneous melanoma was screened out and the level of EBI3 was additionally predicted, and an elevated EBI3 expression was observed (p-value < 0.05)." (PMID 39726752, 2024).
uveitis (1 paper, 2021). An inflammatory process affecting a part of or the entire uvea. "Some reports underscored the promotion of inflammatory diseases by IL-12 and IL-23 (shared p40) and the inhibition of autoimmune diseases, such as uveitis and multiple sclerosis, by IL-27 and IL-35 (shared Ebi3)." (PMID 33816637, 2021). "Therefore, in view of the inhibiting effect on Th17 cell differentiation, Ebi3 and IL27p28 deserve further research and may become potential therapeutic targets of uveitis." (PMID 33816637, 2021).
tumor (52 papers, 2012 to 2026). "Interleukin-35 (IL-35) is an added member of the IL-12 heterodimeric cytokine family, composed of two subunits: EBI3 and P35 subunits, implicated in tumor immune evasion." (PMID 41357575, 2025). "Although the target molecule of EBI3 remains to be identified, the expression of EBI3 is highly associated with tumor growth." (PMID 34603342, 2021). "Nevertheless, the upregulation of EBI3 expression is highly associated with tumor progression and metastasis in a variety of cancers including breast, gastric, lung, pancreatic, cervical, and nasopharyngeal cancers." (PMID 34603342, 2021). "The use of mice deficient in WSX-1, EBI3, or p28 also suggest a role for IL-27 in promoting anti-tumor CD8+ T cell responses." (PMID 31681561, 2019). "Expression of IL-27p28 and EBI3 was also detected in tumor- or ascites-associated leukocytes with myeloid features." (PMID 28255204, 2017). "Other CpGs are associated with genes related to immune function, including T cell regulation and inflammation, tumor initiation and angiogenesis (EBI3), while other genes have been implicated in cancer aggressiveness (AQP9, RIN1)." (PMID 25472429, 2014). "Whereas others reported the production of immunosuppressive cytokines in different conditions and B cell subpopulations, we did not detect an upregulation of genes associated with immunosuppression in tumor-derived B cells, namely Il-12a, Ebi3 (which together form IL-35) and Il-10." (PMID 30972056, 2019). "In line with microarray data, we observed that expression of EBI3 by tumor cells was associated with variable levels of p35 expression by these cells, ranging from undetectable expression to moderate expression by most tumor cells." (PMID 31316915, 2019). "In agreement with the expression pattern of EBI3 and IL12A found in public scRNA-seq tumor datasets, TCGA analysis revealed a positive correlation between EBI3 and IL12A in the majority (20 out of 32) of cancers from the TCGA database." (PMID 40610398, 2025). "Several were most upregulated in specific subsets, such as multi-cytokine in CD8 memory; TIMD4/TIM3 in CD8 CM and γδT; CTLA4/CD38 in Treg, CD4 memory and CD8 CM; and OX40/EBI3 in tumor-infiltrating T cells." (PMID 40903640, 2025). "In the future, a mouse xenograft model will be introduced to verify the role of EBI3 on tumor growth, metastasis, and immune regulation in vivo." (PMID 39726752, 2024). "Quantitative PCR (qPCR) of whole tumor lysate for transcript levels of the cytokines TGFβ (Tgfb1–2), IL10 (Il10), and IL35 (Ebi3 and Il12a), associated with suppressed antitumor immunity, showed reduced levels in Vegfr2Y1173F/+ tumors." (PMID 37651195, 2023). "Second, the IHC data are semiquantitative; additional methods are needed to evaluate and confirm the rates of EBI3 expression in tumor cells." (PMID 39291183, 2022). "Interleukin-35 (IL-35) is a heterodimeric cytokine composed of Epstein-Barr virus-induced gene 3 (EBI3) and IL-12p35 that has recently been shown to play diverse and important roles in the tumor microenvironment (TME)." (PMID 34093586, 2021). "Western blot and immunohistochemistry results indicated that EBI3 and p35 were highly expressed in the tumours of the IL-35 group and less expressed in those of the IL-35 NA group." (PMID 33041668, 2020). "In some cases, cells other than tumor cells, such as infiltrating leukocytes (possibly macrophages or plasma cells based on their morphology) were also positive for EBI3 and p35." (PMID 31316915, 2019). "Of the 75 DLBCL cases tested, 26 (35%) had ≥30% tumor cells positive for both EBI3 and p35 and were scored as IL-35-positive." (PMID 31316915, 2019). "In the 4T1-BALB/c syngeneic tumor model, an upregulation of Ebi3 and Il12a was confirmed in mTAMs compared with pTAMs." (PMID 30218063, 2018). "Several studies have explored the expression of IL-35 in several types of tumours with antibodies specific to EBI3 (refs 28, 29)." (PMID 28102193, 2017).
tumor (continued). "EBI3 and P35 were frequently co-expressed in the cytoplasm of the five types of tumour tissue but they were rarely expressed in the adjacent normal tissues and the adjacent pre-neoplastic lesions." (PMID 28102193, 2017). "Ebi3 expression was increased in Hodgkin’s lymphoma and more Treg cells and inhibitory cytokines were noted in peripheral blood and tumor microenvironments of patients with pancreatic or breast carcinomas." (PMID 28794689, 2017). "Particularly, EBI3 blocking promoted tumor infiltrating Granzyme B+ CTLs and IFN-γ+ CTLs production and restrained CRC cell proliferation through bidirectional reciprocal-regulation STAT3 signaling pathway." (PMID 27247488, 2016). "In the end, the effect of EBI3 on the tumor growth in vivo was investigated by subcutaneous injecting C26 cells containing EBI3 blocking peptide and their corresponding control cells subcutaneously into BALB/c mice." (PMID 27247488, 2016). "Here, we demonstrated evidence that EBI3 assist the tumor escape immune surveillance in CRC by mediating a bidirectional reciprocal-regulation STAT3 signaling pathway to induce antitumor CTL response and suppress tumor growth." (PMID 27247488, 2016). "In summary, we demonstrated evidence that EBI3 associated with IL-12p35, gp130, and p-STAT3 are highly expressed in CRC cells to inhibit antitumor CTL response and promote tumor growth in CRC." (PMID 27247488, 2016). "In consistent with published data, we noted that EBI3 in the tumor microenvironment are likely to be a prerequisite to ensure CRC progression." (PMID 27247488, 2016). "In this work we further tested the role of EBI3 in tumor microenvironment with a EBI3 blocking peptide (EBI3 Bp)." (PMID 27247488, 2016). "The expression of the two IL-27 chains, IL-27A and EBI3, in tumor-associated leukocytes in EOC ascites and tumor tissues suggested a role of endogenous IL-27 in the microenvironment of this tumor." (PMID 26657115, 2015). "Hypomethylated genes in the TNF network were cytokines (CCL3, CCL4, CCL7, CCL8, CCL22, IL21, IL17A, EBI3) that can either stimulate or inhibit tumor growth and progression." (PMID 22768131, 2012). "Notably, EBI3 rs428253 predicted worse OS in EBV-positive patients, whereas rs4740 and rs4905 variants were associated with advanced tumor stage (P=0.024 and P=0.018)." (PMID 41615190, 2026). "EBI3 may contribute to the anti-tumor effects of IL-27, though further research and clinical validation are required to determine its specific applications in tumor immunotherapy." (PMID 40519922, 2025). "It was further found that the reduction of Ebi3 expression level in C1q + cells can restore the anti-tumor killing ability of CD8+ T cells, while the loss of METTL14 expression can reduce the m6A modification level of Ebi3 mRNA in C1q + cells and promote the increase of its transcription level." (PMID 35614935, 2022). "So we assumed that EBI3 may be as a main functional subunit and plays a major role in IL-35 and has different impacts on prognosis based on tumor type." (PMID 39291183, 2022). "IL-35+ DCs and interacting T cells enrich P35 and Ebi3 expression, and mice vaccinated using IL-35+ DCs exhibit enhanced tumor growth and reductions in T cells within the TME, consistent with the ability of this cytokine to constrain intratumoral immune responses." (PMID 34093586, 2021). "The expressions of both EBI3 and IL12A are associated with larger tumor size and Ki‐67 expression." (PMID 33064893, 2020). "Noteworthy, we found an upregulation of EBI3 in the PT region of the lung of these patients, indicating an important function of EBI3, and therefore IL-35 in the tumour microenvironment where not only T cell-mediated immune responses but also immunosuppression takes place." (PMID 30956278, 2019). "Similarly, EBI3-deficient BALB/c or C57BL/6 mice showed reduced antitumor immune responses and enhanced tumor growth when challenged with J558 plasmacytoma or B16 melanoma cells, respectively." (PMID 28255204, 2017).